IL4 (interleukin 4)
Diseases named in the same sentence as IL4 in open-access papers (continued):
Sharing a sentence is not in itself a finding about the gene and the disease.
tumor (continued). "Increased levels of biological mediators such as IL-4, IL-10 and TGF-b, present both in HNSCC and in the microenvironment of other tumors may affect the adaptive immune response, thereby suppressing immune-surveillance and facilitating tumor progression." (PMID 28977830, 2017). "In addition, the evaluation of the cytokines present at primary renal cell cancer site by PCR for freshly isolated RCC TIL, as well as established RCC lines, revealed an increased IL-4 mRNA level in freshly collected RCC TIL and short-term-cultured RCC tumor lines." (PMID 28927416, 2017). "In this respect, Pries and colleagues could show that HNSCC tumor cell lines alone could secrete high levels of IL-6/IL-8 but no significant levels of IL-4 and IL-10 in the absence of infiltrating immune cells." (PMID 28443091, 2017). "Notably, through a side-by-side comparison, cerdulatinib, but not ibrutinib, induced apoptosis of tumor cells in the presence of stromal co-culture and in the presence of combined micro-environmental stimuli including IL-4, CD40L and anti-IgM." (PMID 28088788, 2017). "However, there is no information as to how IR-induced IL-4 expression translates to tumor progression and metastasis." (PMID 27895317, 2016). "Overall, spleen cells produced only low levels of IL-4, regardless of whether the spleen cells were unstimulated or exposed to tumor-conditioned medium, or which group of mice the cells came from." (PMID 27598146, 2016). "IL-4 and IFN-γ are suggested to regulate leukocyte adhesion molecule-1, whereas they take part in the interaction of tumor cells and immune effector cells, and T cell dysfunction in the advanced stage of the disease; therefore, altered cytokine profiles may affect the pathogenesis of the disease." (PMID 26376785, 2016). "CCL7 has been identified as a monocyte attractant produced from certain tumor cells and macrophage, and shown to function as a chemotactic for eosinophil infiltration into the lung tissues in TH2-type pulmonary granuloma, which was blocked by anti-IL-4 treatment." (PMID 27010397, 2016). "Tumor growth in IL-4 mice was less than the tumor growth in non-transgenic mice." (PMID 26993600, 2016). "Based on the results of the tumor challenge and growth, it was concluded that PAP-specific immune activation occurred in the mice treated with the PAP-fused cytokines, and the antitumor effects were significantly enhanced by the additional cytokine (IL2, IL4 and IL7) fusion proteins." (PMID 25632844, 2015). "In addition other signals are necessary to MDSCs activation, including IFN-γ, ligands for Toll-like receptors (TLRs), IL-4, IL-13, and TGF-β, produced mainly by activated T cells and tumor stromal cells after induction by different bacterial and viral products, or as a result of tumor-cell death." (PMID 26161414, 2015). "(data not shown) It is suggested that IL-4 acts indirectly on tumor cells." (PMID 26674732, 2015). "However, NKT cell secretion of IFN-γ, and not IL-4 after an administration of α-GalCer-loaded DCs has been shown to have tumor protective effects." (PMID 26121617, 2015). "However, levels of IL-1α, IL-4, IL-10, IL-13, and TNFα were not significantly altered by tumor growth." (PMID 26347589, 2015). "While IL-4 is a cytokine involved in Th2 responses (which are not appropriate for anti-tumor immunity), IL-10 and TGF-β are cytokines with immunosuppressive functions and thus could be involved in the pro-tumor activities of γδ T cells." (PMID 25538706, 2014). "Importantly, comparison between IL-4 levels produced in the tumor and spleen of tumor-bearing WT and iNKT−/− mice did not reveal significant differences consistent with differential Th2 polarization." (PMID 25349699, 2014).
tumor (continued). "Practicing physical activity in combination with the presence of a tumor produced IL-4 levels that were significantly higher than the IL-4 levels observed in each of the three other groups (P=0.021 vs. no tumor/non-trained; P=0.006 vs. no tumor/trained; P=0.0021 vs. tumor/non-trained)." (PMID 24520305, 2014). "This is puzzling because IL-4 and IL-10 are known to play immunosuppressive roles and yet are being produced alongside proinflammatory cytokines in the presence of premalignant (but not tumor) supernatant." (PMID 24698959, 2014). "Development of TH2 cells, involved in responses against parasites (but detrimental in the setting of anti-tumor responses), is though to be induced by the lack of IL-12 as well as by IL-4, thymic stromal lymphopoietin (TSLP), and Matrix metalloproteinase 2 (MMP-2)." (PMID 24339825, 2013). "Thus, we conclude that the observed effects were indeed due to activation of macrophages by IL-4 and not due to effects of IL-4 on tumor cells or fibroblasts." (PMID 22792213, 2012). "However, when fused to GM-CSF, IL-2, or IL-4, these recombinant molecules elicited anti-tumor immunity when administered without carrier or adjuvant." (PMID 23162790, 2012). "Interestingly, extended co-culture with tumor cells for three weeks resulted in spontaneous M2 polarization of macrophages without IL-4 treatment." (PMID 22792213, 2012). "Additionally, macrophages are M2 educated in co-culture with tumor cells after three weeks in absence of fibroblasts and IL-4 stimulation." (PMID 22792213, 2012). "The lungs of tumor-bearing mice contained 3.5-times more IGF-1 than naïve littermates, and media conditioned by freshly isolated tumor-educated macrophages contained more IGF-1 than media conditioned by naïve macrophages; IL-4 stimulated IGF-1 production by both macrophage subsets." (PMID 21699731, 2011). "Given that this tumor-inhibitory role could be compromised by antagonistic Th2 (IL13, IL4) and TGFB pathways, we hypothesized that tumours exhibiting simultaneous high Th1 and low TGFB activity may exhibit a better prognosis than tumors stratified by each pathway alone." (PMID 21050467, 2010). "In order to examine the differences between IFN-DC and conventional IL-4/TNF-DC, we compared the morphology, immunophenotype, functional efficacy and gene expression profiles of these cell preparations with regard to their usefullness in anti-tumor vaccination strategies." (PMID 17894866, 2007). "To evaluate whether cytokine expression from tumour-stimulated CD8+ T cells segregated in discrete IFN-γ+/IL-4− and IFN-γ-/IL-4+ subsets we took advantage of recently developed flow cytometric techniques for the detection of intracellular cytokine expression at the single cell level." (PMID 11857027, 2002). "However, although successful in treatment studies, neither wild-type nor combined IL-2 + IL-4 expressing cells were able to vaccinate animals against a subsequent challenge with live wild-type tumour." (PMID 8679459, 1996). "However, when cells expressing single cytokines IL-2 or IL-4 were mixed and injected at the same site, in comparison with the clonal population of cells expressing combined IL-2 + IL-4, tumour growth was characteristic of IL-4 alone rather than IL-2 + IL-4." (PMID 8679459, 1996). "The benefit of combined IL-2 + IL-4 expression results from a local rather than systemic effect as the growth of tumours from cells expressing IL-2 or IL-4 alone injected at distant sites was comparable with a single inoculation of cells expressing either cytokine alone." (PMID 8679459, 1996). "Histological examination of tumours expressing either IL-2 or IL-4 alone shows a non-specific inflammatory reaction with an increased tissue infiltrate of immune effectors (monocytes/macrophages, lymphocytes, granulocytes) localised around the tumour." (PMID 8679459, 1996). "However the mechanisms of action of secreted IL-2 and IL-4 have not been compared in a single rodent tumour." (PMID 8347485, 1993).
tumor (continued). "Regarding the cytokine profile, notable modulations were observed in the levels of IL-1β, IL-4, IL-6, IL-10, IL-17A, and TNF-α, particularly in the FMT groups, indicating an influence on the local immune response that could contribute to shaping the tumor microenvironment." (PMID 41614846, 2025). "Furthermore, tumor-produced factors (e.g., IL-4, IL-10, TGFß1, and PGE2) contribute significantly to the functional polarization of monocytes/macrophages into immunosuppressive cells, highlighting the intricate interplay between tumor cells and the immune system." (PMID 39410029, 2024). "However, IL4 mediated macrophage activation and did not affect tumor cell apoptosis." (PMID 37325064, 2023). "In particular, oestrogens may favour an immunosuppressive TME by enhancing Th2 responses, tumour-promoting cytokines (IL-4, IL-6, IL-17A and TNF) and M2 TAM infiltrations, unlike M1 TAM infiltration and Th1 responses, which are commonly joined with Th1 cytokines (IL-12 and IFN)." (PMID 38332913, 2023). "Awaji found that KRAS mutation could promote the secretion of paracrine factors such as IL4, IL10, and IL13 in tumor cells and simultaneously activate CXCR2 signaling in CAFs, resulting in the formation of a secreted CAF phenotype by activating NF-κB signaling and promoting tumor progression." (PMID 36076911, 2022). "Furthermore, the expression of cytokines IL-1β and IL-6 in the GC + PTT group was both 1.7-fold higher than that in the PBS + PTT group, whereas, the expression of the cytokine IL-4 with a pro-tumor function was not significantly different between all the groups." (PMID 32042338, 2020). "Moreover, when tumor-bearing mice were injected with αGC, intratumoral DCs and iNKT cells showed less STAT6 phosphorylation and IFNγ production, respectively, than cells from the spleen, although similar production of IL4 was detected for the intratumoral iNKT cells and splenic iNKT cells." (PMID 31160756, 2020). "In addition, IL4 and IL13 could act as signaling molecules in the tumor microenvironment." (PMID 31540495, 2019). "Moreover, blockade of IL-4 resulted in overexpression of pro-inflammatory cytokines (CXCL10, IL-1β, IL-15, IL-10 and IL-6) and lower expression of immunosuppressive molecules (Foxo3, IDO1 and PD-L1) as compared to cryo-thermal eosinophils + tumour-bearing DCs group." (PMID 31519961, 2019). "Interestingly, IL-4, IL-6, IL-10 and GM-CSF have no regulatory effects on the expression of B7-H4 on tumor cells, indicating that the expression of B7-H4 in tumor cells may be functionally distinct and differently regulated compared with APCs." (PMID 22013483, 2011). "However, based on the results in this study, we conclude that Day-4 DCs generated using GM-CSF, IL-4 and serum-free AIM-V media and pulsed with whole tumor antigen are superior to Day-2 DCs generated in the same culture condition for priming strong and specific tumor-specific T cell responses." (PMID 22194898, 2011). "Importantly for the co-variance argument raised above, IL-4 also increases the expression of CB1 receptors in lymphocytes so we elected to focus on that molecule as a “test of concept” that a component of the tumour microenvironment can influence FAAH activity." (PMID 20808855, 2010). "Therefore, IL-4 does not appear to be an autocrine growth factor for tumour cell lines." (PMID 11870521, 2002). "While we do not exclude the possibility that host cytokines such as IL-4 synergize with FABP5 signaling, our data highlight the sufficiency of tumor-derived FABP5 to remodel the immune microenvironment, even in the presence of competing endogenous signals." (PMID 41035647, 2025). "Moreover, levels of IL-10 and IL-4 decreased significantly in CMU-Pb-L5 group, indicating that L.p CMU-Pb-L5 intervention could reduce the expression of immunosuppressive cytokines in vivo, thus improving the tumor immune microenvironment and inhibiting tumor growth." (PMID 39439459, 2024).
tumor (continued). "In contrast, correlations between DKK1 and cytokines mainly deriving from or acting on lymphocytes such as IL2, IL4, or IL17 were weaker or absent in tumor tissues." (PMID 36539532, 2022). "Similar to what was observed in Braf/Pten tumor-draining ILNs, MC903 treatment–promoted GATA3+ Tregs in Braf ELNs exhibited signature expression of ST2, OX40, and PD-1, but not IL-4 and IL-13 which were only detected in GATA3+ Th2 cells." (PMID 36107619, 2022). "Therefore, IL-4 itself may have a negative impact on tumor development." (PMID 33670758, 2021). "Consistently, the observations here reported show that in vitro IL4 is able to modulate myogenesis but not to affect C26 tumour cell growth curve, suggesting that while the effects on muscle are directly mediated by IL4, those on the tumour could depend on additional mediators." (PMID 32103619, 2020). "However, despite being increased in size, tumours at Day 31 in IL4‐treated C26 hosts present with conspicuous necrotic areas and with a high number of infiltrating inflammatory/immune cells (CD8+ lymphocytes and type II macrophages), which could be involved in tumour cytotoxicity and necrosis." (PMID 32103619, 2020). "In our study, Jag2 deletion in DCs did not result in any major changes in anti-tumor T-cell responses, such as IFN-γ production but had a negative effect on the number of IL-4 producing cells, consistent with the role of Jag2 in supporting Th2 differentiation." (PMID 30940183, 2019). "Treatment with various cytokines, including IFN-γ, IL-2, IL-4, and IL-6, did not increase VISTA expression in tumour cells." (PMID 30382166, 2019). "It was suggested that ERK contribute to M2 phenotype for tumor-infiltrating macrophages (TIMs), but the role of ERK has not be proven to be essential for IL-4-activated macrophages as a general concept." (PMID 29422898, 2018). "There were no group differences in tumor protein concentrations of IFN-γ, IL-2, IL-4, IL-5, IL-10, and IL-12p70 (p > 0.05 data not shown)." (PMID 28811490, 2017). "In this study, the significant decline of IL-4 but no change in the production of IL-12 and TNF-α was observed, which showed the activation of Th1 and NK cells in the tumor sites." (PMID 27246873, 2016). "TIL155-C1 and TIL155-C2 secreted GM-CSF, IL-2, and IFN-γ but did not secrete IL-4, IL-10, or transforming growth factor (TGF)-β after exposure to 155mel tumor cells." (PMID 25993655, 2015). "The co-administration of PAP-GMCSF, -IL2, -IL4 and -IL7 significantly prevented tumor induction and inhibited tumor growth in the PAP-expressing tumors, yet not in the PSA-expressing tumors." (PMID 25632844, 2015). "CD4 T cells harvested from mice treated with anti-PD-L1 plus anti-LAG-3 or anti-TIM-3 also released IFN-γ when stimulated with 5T33-CIITA cells, but there was no spontaneous or tumor-induced release of IFN-γ, IL-4 and IL-5." (PMID 25614821, 2015). "Th1 polarization was demonstrated after stimulation with CTA-pulsed DCs and co-culture with tumor cells, by detecting more than 50-fold increase in IFN-γ and TNF-α production and no significant change in IL-4, IL-5, and IL-10 levels, using ELISA." (PMID 25739119, 2015). "The simultaneous intraperitoneal administration of PAP-GMCSF, -IL2, -IL4 and -IL7 significantly prevented tumor induction and inhibited the tumor growth in the PAP-expressing tumors, yet not in the PSA-expressing tumors." (PMID 25632844, 2015). "When stimulated by tumor cells and an anti-CD3 antibody, Vγ1 T cells express IFN-γ and GM-CSF, but not IL-1β, TNF-α, IL-12, IL-2, IL-4, IL-10, or TGF-β." (PMID 25538706, 2014). "Other cytokines analyzed (GM-CSF, IL-2, IL-4, IL-10, IL-12 (p70), IL-13, IL-17, VEGF and TNFα) were below detection level of the assay, or did not exhibit any significant changes upon tumor growth or Delta24-RGD treatment (results not shown)." (PMID 24866126, 2014).
tumor (continued). "For example, MCP-1 and IL-8 levels progressively increased during the course of radiation, while other cytokines, such as IL-4 and EGF were elevated in closer proximity to tumor with no trend for an increase in concentration during the course of radiation." (PMID 22537315, 2012). "Serum IL-17, IFN-γ, and IL-4 levels were not detectable and serum TNF-α level was low in healthy mice in both groups, i.e. before tumor inoculation." (PMID 21484786, 2011). "Interleukin-4 (IL4), a key cytokine for Th2 differentiation, binds to IL4R, forming the type I IL4 receptor (IL4R-IL2RG) on lymphoid cells and the type II IL4 receptor (IL4R-IL13RA1) on non-lymphoid and tumor cells." (PMID 39941924, 2025). "In U87 cells, the selective decrease in IL-4, but not IL-8 upon treatment implies that EU and BCA may specifically interfere with the apoptotic signaling pathways, which could reduce tumor growth." (PMID 39796096, 2024). "Some cytokines in TME, such as macrophage colony stimulating factor, IL-4, IL-6, IL-10, TGF-β and VEGF can alter the differentiation of DCs and inhibit the activation and maturation of DCs, resulting in a lack of mature and functional DCs in tumor patients." (PMID 37064113, 2023). "MDSC-DCs were induced from splenocytes of these mice by granulocyte macrophage–colony stimulating factor/interleukin-4 with or without all-trans-retinoic acid (ATRA) in vitro for 7 days, then incubated with tumor-cell-lysis to treat mouse models for total three doses." (PMID 35707772, 2022). "According to existing reports, increased Th2 marker levels accelerate the secretion of interleukin(IL)-10 and IL-4 and inhibit cellular immune function, and the GATA3/T-bet(G/T) ratio of tumor-infiltrating lymphoid cells is an independent negative predictive marker for survival." (PMID 34221962, 2021). "However, treatment with several cytokines, including IFN-γ, IL-2, IL-4, and IL-6, did not raise VISTA expression in tumor cells." (PMID 34728682, 2021). "Blocking TGF-β signaling in CD4+ T cells but not CD8+ T cells restrained tumor growth by remodeling the TME and inducing tumor vasculature reorganization, leading to cancer cell death; this process was dependent on the TH2 cytokine interleukin-4 (IL-4), but not the TH1 cytokine interferon-γ (IFN-γ)." (PMID 34917620, 2021). "Based on our data, preoperative serum IL-4 levels may have a role in predicting TA-specific T cell responses and RFS, regardless of the tumor stage." (PMID 33255425, 2020). "Besides TGFβ, other negative/regulatory cytokines in the tumor environment limit T cell persistence and activity—these include IL10, IL13, and IL4." (PMID 31024832, 2019). "But IL-4 could not suppress the progression of RCC, even exhibit a possible “positive” activity of tumor progression." (PMID 29137245, 2017). "Naturally occurring tumour‐specific HLA‐II‐restricted CD4+ T cells and those engineered to express HLA‐I‐restricted tumour TCRs have been reported to exhibit a mainly Th1 phenotype, where cells typically produce IFN‐γ, TNF‐α and IL‐2 but not IL‐4, IL‐5 or IL‐10." (PMID 27324616, 2017). "Mature DCs were derived from peripheral blood monocytes, culture in the presence of granulocyte-macrophage colony-stimulating factor, interleukin 4, and tumor necrosis factor alpha with or without addition of IFN-gamma, loaded with tumor lysate, and finally further injected into a groin lymph node." (PMID 25328756, 2014). "Analysis of the profiles of cytokines in the culture supernatants showed that the tumor-activated γδ T cells secreted substantially more Th1-prone cytokines such as IFN-γ, IL-1, IL-6, and IL-12, but not IL-4 and IL-10, than peripheral-derived γδ T cells did (n = 5)." (PMID 24741609, 2014). "Indeed, even if some tumor antigen specific CD4 Treg clones were also found to secrete a diverse panel of cytokines such as IFN-γ, GM-CSF, TNF and IL5 or IL4 and IL10, in vitro, none of them was able to secrete IL2." (PMID 23284752, 2012).